SCARNA8 (small Cajal body-specific RNA 8)
Synonyms: U92
Gene: Small Cajal body-specific RNA gene on chromosome 9 (19,063,656 to 19,063,786, reverse strand). Ensembl gene ENSG00000251733.
Gene Ontology:
Biological process: RNA processing
Cellular component: Cajal body; nucleolus
Homologues: Orthologues: chimpanzee SCARNA8 (99% identical), rabbit SCARNA8 (92% identical), guinea pig SCARNA8 (92% identical), zebrafish SCARNA8 (71% identical).